MYC (MYC proto-oncogene, bHLH transcription factor)
Diseases named in the same sentence as MYC in open-access papers (continued):
Sharing a sentence is not in itself a finding about the gene and the disease.
cancer (continued). "Three MYC‐induced and eight MYC‐repressed ncRNAs are involved in the regulation of aerobic glycolysis, a feature of cancer cells." (PMID 30451365, 2019). "Overexpression of MYC contributes to development as well as the progression of almost all the cancer types including HCC37." (PMID 30760754, 2019). "By comparison, modeling the oncogenic output of MYC deregulation at a level that reflects incipient human cancer is more challenging." (PMID 31032816, 2019). "Our findings raise the possibility that c-MYC can be targeted through the IRE1α-XBP1s pathway not only in PCa, but also in other cancer types where c-MYC is important." (PMID 30679434, 2019). "Many of the miRNAs that can directly downregulate MYC by binding to the MYC mRNA, show reduced levels in cancer." (PMID 30451365, 2019). "MYC is arguably the most clinically-relevant oncogene, important in many cancers besides ALL, but MYC’s contrasting actions in distinct neoplasias remain largely unexplored." (PMID 30111845, 2019). "MYC expression has been shown to be highly reliant on PVT1—PVT1 is increased in nearly 98% of cancers displaying overexpression of MYC." (PMID 31508377, 2019). "The MYC TAD contains many conserved CTCF-binding sites in human cancer and normal somatic cell lines." (PMID 31127282, 2019). "Kinome-wide siRNA library screening identified several therapeutic targets, reported as synthetic lethal targets for MYC-addicted cancers." (PMID 31848373, 2019). "In various cancers, MYC-dependent transcription requires the critical transcriptional assembly and/or chromatin-modifying enzyme complexes influencing cell division and survival." (PMID 31288832, 2019). "The proto-oncogene MYC influences multiple seemingly unrelated phenotypes, and it is commonly amplified or overexpressed in human cancers." (PMID 31142021, 2019). "Elevated c-MYC expression are observed in 80% of human cancer cells, including TNBC, which promotes tumorigenesis." (PMID 31584090, 2019). "The immunohistochemistry (IHC) findings for each of the cancers showed that neoplastic cells were heterogenous in their nuclear and cytoplasmic expression of MYC, HDAC2 and TFE3." (PMID 31399583, 2019). "MYC amplification leads to stimulation of a number of pathways involved in cancer progression and therapy resistance." (PMID 31455317, 2019). "This work reveals a novel anticancer mechanism of PGG via downregulation of MYC expression and establishes a therapeutic rationale for treatment of MYC overexpressing cancers using PGG." (PMID 30760754, 2019). "The applicability of the ABv+anti-PD-1 combination for treating other cancer types with high MYC and BCL-2/BCL-XL status is currently being investigated in preclinical models." (PMID 30728358, 2019). "Combined with a kinome-wide siRNA library screen, our results identified UVM as a MYC-driven cancer, with several therapeutic targets." (PMID 31848373, 2019). "Under normoxia, a high level of endogenous c-MYC is found in several cancer cell types: c-MYC also upregulates glycolysis." (PMID 31600993, 2019). "Previous studies have revealed that in MYC-driven cancers, MYC directly upregulates the transcription of several genes encoding splicing factors, as well as genes encoding factors involved in snRNP assembly, including SNRPB33,34." (PMID 31511502, 2019). "Based on these studies, an approach to stabilizing the G4s formed in the regulatory element and attenuating the promoter activity by ligands has also been studied for cancer therapy, similar to the small molecule targeting of c-MYC G4." (PMID 30682877, 2019). "JQ1, a specific and competitive inhibitor of BRD4, can decrease MYC expression levels and induce apoptosis in diverse human cancers, including medulloblastoma, lung adenocarcinoma, glioblastoma, and myeloid leukemia." (PMID 30770740, 2019).
cancer (continued). "In all, these evidences suggest that rewiring the rRNA maturation pathway represents an additional strategy exploited by oncogenes, such as MYC, to speed up ribosome biogenesis in cancer." (PMID 31533350, 2019). "In particular, MYC is an oncogene involved in the initiation and progression of various types of cancer through its collaborative functions with other cancer-related genes." (PMID 30863497, 2019). "Given the critical role for c-MYC in regulating glycolysis in cancer cells, ESCs also employ the myc genes to regulate metabolism probably by similar mechanisms to those used for maintaining rapid cell proliferation." (PMID 31067778, 2019). "Many approaches have been developed to model MYC in cancer, including cancer cell lines and genetically engineered mouse models (GEMMs)." (PMID 31350286, 2019). "It was initially assumed that factors that influence cancer aggressiveness, such as TNM stage and race, associates with MYC status." (PMID 31905596, 2019). "MYC is located on chromosome 8 in humans and has an equivalent in mice (on chromosome 15), and MYC expression is significantly increased in cancer." (PMID 30925926, 2019). "Previous studies suggest that the LIN28/let-7/c-MYC pathway played a significant role in the development and progression of several cancers types." (PMID 31744257, 2019). "They found MYC up-regulated UFD1 in T-ALL, and allelic loss of zebrafish ufd1 induced T-ALL apoptosis, impairing cancer progression." (PMID 31731471, 2019). "Many cancers have genetic MYC activation, which can collaborate with hypoxia inducible factors (HIFs) to confer metabolic advantages to cancer cells for surviving in a hypoxic microenvironment." (PMID 31336613, 2019). "Cyclin-dependent kinase 5 (CDK5), a generally dysregulated protein in various carcinomas, can mediate c-MYC phosphorylation at Ser-62 site." (PMID 31496920, 2019). "The top five upregulated DEGs, including CDK1, CCNB1, TOP2A, MYC, and PCNA, were associated with cell mitosis and involved in the development of cancer." (PMID 30092828, 2018). "In physiological conditions, MYC couples mitochondrial biogenesis with cell-cycle progression, whereas once deregulated in cancer it stimulates mitochondrial metabolism to support rapid cell growth." (PMID 29740540, 2018). "We considered few criteria to enable the peptides with anti-cancer properties and selective affinity for c-MYC quadruplex." (PMID 30239898, 2018). "It has also been found that the disordered expression of MYC is common in human cancers and is closely related to the maintenance of aggressive of cancer stem cell populations." (PMID 29482638, 2018). "GCN5 and TRRAP, other components of SAGA, interact with the MYC oncoprotein in mammalian cells, which is the most important protein in cancers." (PMID 29555684, 2018). "In cancer of different histotypes MYC gene amplification or upregulation drive tumorigenesis by inducing stemness, promoting cell growth and proliferation, and hampering cell differentiation." (PMID 29435159, 2018). "For instance, the c-MYC transcription factor, often dysregulated in human cancers, increases protein synthesis by controlling the expression of multiple components involved in ribosome biogenesis and translation process." (PMID 29674660, 2018). "PVT1 is a well-known oncogenic lncRNA which is often co-amplified with the proto-oncogene MYC (MYC proto-oncogene, bHLH transcription factor) and is required for elevated MYC expression in cancer." (PMID 29702599, 2018). "c-MYC binds to an E-box motif at VEGF-A promoter which positively regulates its transcription in cancer cells." (PMID 30239898, 2018).
cancer (continued). "For example, the lncRNA PVT1 has been shown to be required for increasing MYC protein stability and high expression levels in 8q24-amplified cancers." (PMID 29466962, 2018). "By contrast, MYC is a well characterized protooncogene that is aberrantly overexpressed in many cancer types." (PMID 30261014, 2018). "A new small molecular inhibitor, JQ1, targeting BRD4, which recognizes the acetylated lysine residues, has been shown to induce cell cycle arrest in different cancers by inhibiting MYC oncogene." (PMID 29996811, 2018). "SYUIO-05 significantly arrested cell proliferation of several cancer cell lines and downregulated MYC transcription." (PMID 30597997, 2018). "Overall, targeting MYC-regulated rRNA transcription and ribogenesis in two distinct cell sites is an unconventional approach worth of consideration for treating MYC-driven cancer." (PMID 29435159, 2018). "Oncogenic MYC influences cancer cell metabolism by increasing the expression of glucose and glutamine transporters and promoting glucose and glutamine metabolism." (PMID 30103560, 2018). "In both cases, the ratios of PGC-1α to HIF-1α or MYC function as rheostats that will dictate the propensity of cancer cells to rely on glycolysis or OXPHOS for survival." (PMID 29629336, 2018). "In this study we provide evidence that MYC-induced rRNA transcription both in the nucleolus and mitochondrion concur to promote the proliferation of MYC-overexpressing cancer cells." (PMID 29435159, 2018). "Searching for alternative therapeutic options for treating aggressive MYC‐driven cancers is thus of high clinical interest." (PMID 29789342, 2018). "Our study indicates that these cancer cells are MYC-positive, resembling crypt stem cells or progenitors." (PMID 30223484, 2018). "Critically, CDK9-mediated transcription of MCL-1 and MYC plays an important role in growth and survival of cancer cells, and dysregulation of this component of the CDK9 pathway is prominent in a number of hematologic malignancies." (PMID 29471852, 2018). "MYC and FoxO are known in cancer metabolic adaptation and reprogramming, and the regulation of this axis is connected with the Akt/mTOR signaling pathway." (PMID 30515268, 2018). "We found that CEP55 is a downstream effector of MAPK signaling through MYC oncogene, which has a central role in transformation, tumorigenesis, and genomic instability, and MYC is deregulated in many cancers." (PMID 30108112, 2018). "Since MYC is upregulated in MM and, among others, enhances PD-L1 and CD47 membrane translocation in cancer cells, it is possible that MYC also regulates PD-L1 and CD47 expression in MM cells." (PMID 29783691, 2018). "Especially, for a gene that regulates cell growth such as MYC, dysregulated expression can trigger some life-threatening diseases such as cancer." (PMID 30499017, 2018). "So far, we observed that KR12C is the best peptide candidate that selectively repressed c-MYC promoter activation in cancer cells." (PMID 30239898, 2018). "Our data show that inhibition of CREBBP/EP300 bromodomains can interfere with transcriptional outputs driven by oncogenes, such as GATA1 and MYC that function as transcription factors in cancer cells." (PMID 29884215, 2018). "MYC is overexpressed in various human cancers, and its potential to reprogram the cellular metabolism in cancer is well-recognized." (PMID 29907133, 2018). "MYC upregulation is related to the metabolism reprogramming in cancer cells, influencing a variety of aspects." (PMID 29349517, 2018). "Correlations between LYL1 amplification and increased expression levels of cancer-related genes (MYC, CDK6, PRKACA, and ERBB2) are also observed." (PMID 29716549, 2018). "GSEA revealed that genes associated with cancer stem cells (CSC) (e.g., NES, TSPAN8, DPPP, DNAJC12, and MYC) were highly ranked and comprised 70% of the top 25 genes differentially upregulated in the DTX-resistant cells." (PMID 30100995, 2018).
cancer (continued). "MYC overexpression is found in many cancers, and MYC overexpression sensitizes cells to apoptosis, enabling targeting a gene that is synthetic lethal to a cancer-relevant MYC overexpression should kill only cancer cells but spare normal counterparts." (PMID 29527331, 2018). "Further, upregulated MYC in different cancers silence the circadian clock and promotes cell proliferation while downregulation of MYC activates the clock and reduces proliferation." (PMID 30386298, 2018). "Active in DAOY and D283med MB cancer stem cells Efficiently reduced the metabolic activity in MYC-MB cells." (PMID 30560106, 2018). "This cancer-promoting activity correlates with the Warburg effect through the activation of the SRC/ERK/c-MYC/PFKFB2 pathway." (PMID 29523788, 2018). "USP28 is a deubiquitinase that has been shown to stabalise LSD1 and MYC, an important regulator of gene expression, to promote a cancer stem-cell like state and proliferation." (PMID 30323900, 2018). "First, we confirmed broad spectrum activity of plumbagin by testing its effects on the proliferation of human (ECC1, SKOV3, OVCAR3 and MCF7) and murine (4T1 and MYC-HRAS MOSE) cancer cell lines." (PMID 29348410, 2018). "The miR-17 family (miR-17, miR-20a, miR 20-b, miR 106-a, miR 106-b, miR-93) and MYC expression was examined in human HCC from the cancer genome atlas (TCGA)." (PMID 29464015, 2018). "We further validated these results through monitoring the expression profiles of different oncogenes and apoptosis markers in order to deduce the mechanism how G-quadruplex stabilization at c-MYC promoter triggered selective apoptosis in cancer cells." (PMID 30239898, 2018). "Chromosome 8q24 is the most frequently amplified locus in many cancers, with MYC being the most likely oncogene at this locus." (PMID 30524948, 2018). "In particular, lactate is used by cancer cells as an inflammatory mediator driving growth through MYC, itself shown to be programming inflammation." (PMID 30627563, 2018). "We find that these diverse cancer-specific super-enhancers, differing in size and location, interact with the MYC gene through a common and conserved CTCF binding site located 2 kb upstream of the MYC promoter." (PMID 29641996, 2018). "Other anti-oxidant systems such as peroxiredoxins, which are induced by MYC, are also highly expressed in many cancer types." (PMID 30197878, 2018). "The c-MYC TF is an attractive target for cancer therapy because of the role that excessive c-MYC levels play in a broad spectrum of aggressive cancers, but direct pharmacologic inhibition of c-MYC remains an elusive challenge in drug discovery." (PMID 29641996, 2018). "Our study results also have provided further support that the Wnt/β-catenin/MYC/Sox2 axis is the key regulator of cancer stemness in ALK+ALCL." (PMID 29609590, 2018). "MYC, a multifunctional oncogene located on human chromosome 8q24.21, has been shown to be amplified and overexpressed in many types of human cancers, including ovarian cancer, esophageal cancer, neuroblastoma, sarcoma, lung cancer, and BCas." (PMID 29523126, 2018). "Our results have further substantiated the importance of the Wnt/β-catenin/MYC/Sox2 axis in conferring the cancer stem-like phenotype in ALK+ALCL." (PMID 29609590, 2018). "This is consistent with the previous reports that iBETs achieve therapeutic effect in multiple cancer types by targeting c-MYC pathway." (PMID 30093685, 2018). "Several research groups are designing small molecules to stabilize the c-MYC promoter quadruplex as a strategy to develop potential therapies for treatment of human cancers." (PMID 30312328, 2018). "Second, we found that atuveciclib treatment decreased protein levels of MYC and MCL1, two major pro-tumorigenic factors regulated by RNA Pol II that are often associated with poor clinical outcomes in many cancer types including TNBC." (PMID 30647871, 2018).
cancer (continued). "Targeting MYC-regulated rRNA transcription and ribogenesis in both the nucleolus and mitochondrion seems to be a novel approach worth of consideration for treating MYC-driven cancer." (PMID 29435159, 2018). "Altogether, these results suggest that MYC activation rendered cancer cells vulnerable to T‐025‐mediated CLK inhibition." (PMID 29769258, 2018). "Activation of RIG‐I in the cancer cells led to NOTCH/MYC pathway activation in fibroblasts which, in turn, enhanced stromal RN7SL1 availability, thus establishing a positive feed‐back loop." (PMID 29280568, 2018). "Here, we describe DC-34, a small molecule that potently downregulates MYC transcription in cancer cells by a G4-dependent mechanism." (PMID 30315240, 2018). "XBP1 and MYC, both known promoters of tumorigenicity and cancer progression in diverse cancer forms, were predicted as activated." (PMID 30419021, 2018). "Aberrant MYC activity, resulting from chromosomal translocations, gene amplifications or increased mRNA/protein stability, is found in over half of all human cancers." (PMID 28748451, 2018). "The CDK7 inhibitor THZ1 and BRD4 inhibitor JQ1 can efficiently target MYC driven transcriptional amplification in other types of cancers, here we studied the potential role of THZ1 and JQ1 in regulation of ostesosarcoma." (PMID 29644114, 2018). "Amplification of MYC directly drives the tumorigenesis of many cancers by regulation of genes necessary for cell proliferation, cell invasion, and metastasis." (PMID 30382079, 2018). "The top scoring TF motifs in cancer cells that associated with sensitive H3K4me3 peak width dynamics tended to involve cancer-associated TFs such as c-MYC and ETS in cancer cells and liver-specific TFs such as RXR and ESRRB in liver." (PMID 29769529, 2018). "This is consistent with the notion that it is the deregulation of MYC expression, rather than altered or neomorphic changes in its protein function, that is at the root of MYC driven cancers." (PMID 30054853, 2018). "We show that CLK inhibitor is more effective against MYC‐activated cancer, consistent with previous reports that MYC‐driven cancers are vulnerable to spliceosome inhibition." (PMID 29769258, 2018). "In particular, one of these molecules, CX-5461, which targets Pol I-mediated rRNA transcription, proved to be effective in in vitro and preclinical MYC-driven cancer cell models." (PMID 29435159, 2018). "MYC is a transcription factor that modulates the gene expression of thousands of genes that regulate many programs which are hallmarks of cancer including: metabolism, proliferation, self-renewal, and survival." (PMID 29464015, 2018). "Since a high fraction of human cancers have MYC over-expression, MYC is an attractive cancer target." (PMID 30108681, 2018). "MYC is a key regulator of proliferation and its deregulation can promote oncogenesis in various types of cancer." (PMID 29463565, 2018). "Dysregulated activation of MYC transcription by superenhancers on the chromatin has been shown to be a driver in the development of many cancers." (PMID 30459933, 2018). "We rationalized to combine miR-34a and PLK1-siRNA in order to attack distinct molecular defects in this cancer while inhibiting MYC, a common target of PLK118 and miR-34a19." (PMID 29295989, 2018). "The miR-17~92 cluster is a known transcriptional target of MYC and has oncogenic properties in several cancer types." (PMID 29795787, 2018). "In this cancer type, the Wnt/β-catenin/MYC/Sox2 axis is an important regulator of cancer cell plasticity." (PMID 29609590, 2018). "Bromodomain and extra-terminal domain (BET) proteins regulate the transcription of many genes including c-MYC, a proto-oncogene, which is upregulated in many types of cancers." (PMID 30333915, 2018). "Co-amplification of MYC with MCL-1 or BCLX is common in cancer and in cell culture and mouse models increased BCL-2-like proteins, and MYC is a potent oncogenic combination." (PMID 29769323, 2018).